ESRRA (estrogen related receptor alpha)
Diseases named in the same sentence as ESRRA in open-access papers (continued):
Sharing a sentence is not in itself a finding about the gene and the disease.
cancer (153 papers, 2009 to 2026). A tumor composed of atypical neoplastic, often pleomorphic cells that invade other tissues. "Estrogen-related receptor alpha (ERRα) is a central regulator of cellular energy metabolism associated with poor cancer prognosis." (PMID 37864196, 2023). "To explore the mechanism underlying the ESRRA mediated regulation of cancer cell proliferation and invasion, we analysed the levels of ESRRA target genes WNT11 and OPN by overexpressing and knocking down its expression." (PMID 26639757, 2015). "Notably, ESRRA, an orphan nuclear receptor implicated in cancer progression and resistance to immunotherapy, was identified as a key hit49,50." (PMID 40593467, 2025). "Furthermore, high expression of estrogen‐related receptor alpha (ERRα) is considered a detrimental factor associated with malignant progression and poorer overall prognosis in various cancer types." (PMID 39506810, 2024). "Peroxisome proliferator-activated receptor-gamma coactivator (PGC)-1alpha, a cotranscription factor, causes the activation of mitochondrial activity-associated transcription factors, such as estrogen-related receptor-alpha (ERRalpha), thereby regulating cancer migration and angiogenesis." (PMID 27271583, 2016). "Our findings reveal that ESRRA predominantly acts as an oncogene in multiple cancer types, whereas ESRRB and ESRRG exhibit distinct roles across different tumors." (PMID 40356747, 2025). "utilized in silico multi-omics approaches (BipotentR) to identify tumor-specific regulators of cancer immunity and discovered that ESRRA expression is significantly elevated in patients that are resistant to immunotherapy." (PMID 40356747, 2025). "Meanwhile, in most cancer types, a noteworthy positive connection was observed between ESRRA and TAP1 (belonging to MHC) and TNFRSF14." (PMID 40356747, 2025). "Specifically, in most cancer types, ESRRA positively correlates with TNFRSF14, and ESRRG with CD160." (PMID 40356747, 2025). "One such example is the estrogen-related receptor alpha (ERRα), a ubiquitously expressed orphan nuclear receptor, abundant in high-energy-demand tissues such as the heart, kidneys and cancer cells." (PMID 37175690, 2023). "Several enzymes in metabolic pathways of proliferating cancer cells control the transcription of ESRRA, depending on the energy requirement." (PMID 36517562, 2022). "In previous studies, overexpression of ESRRA was exhibited to promote cancer cell growth and proliferation." (PMID 36517562, 2022). "Estrogen-related receptor alpha (ERRα), an orphan nuclear receptor, is important in regulating the signaling pathway in cancer." (PMID 33591949, 2021). "As to the molecular mechanism behind, estrogen-related receptor alpha (ERRα) was reported to participate in the TGF-β-induced EMT through cancer–stromal interactions in EC cells." (PMID 35095892, 2021). "Although ESRRA activity is well-characterized in several types of cancer, recent reports suggest that it also has an important role in metabolic diseases." (PMID 32121253, 2020). "PGC-1α, along with ERRα (estrogen related receptor alpha), were also instrumental in reductive carboxylation, where glutamine is converted to citrate for anabolic processes to sustain cancer cell growth." (PMID 33266219, 2020). "Several characteristics of the ESRRA-C11orf20 rearrangement reinforce themes emerging from high-resolution studies of both normal human genetic variation and cancer-specific genomic alterations." (PMID 21949640, 2011). "In cancers that are resistant to immunotherapy, ESRRA is abundantly expressed." (PMID 40356747, 2025). "Taken together, these results suggest that kaempferol exerts its anti-cancer effects in EC cells through the induction of apoptosis and modulation of the cell cycle, which may be mediated by the inhibition of ESRRA." (PMID 36932403, 2023). "PIK3CA, CBFB, CDC27, MAP3K1, and ESRRA were among the genes that were cancer drivers." (PMID 37454130, 2023).
cancer (continued). "SP1 and ESRRA, are instead associated with anti-cancer compounds which have not been tested in SCI thus far." (PMID 29758010, 2018). "A good candidate could be the transcription factor estrogen-related receptor alpha (ERRα) because of its ability to regulate energy metabolism, mitochondrial biogenesis and signalings related to cancer progression." (PMID 26312764, 2015). "Given the role of ESRRA in tumorigenesis, not much is known about the mechanism underlying its upregulation in cancers." (PMID 26639757, 2015). "Upregulation of ESRRA in several cancers, including OSCC, suggests that it could be used as a therapeutic target." (PMID 26639757, 2015). "These small molecules were incorporated into PROTACs to regulate the degradation of various cancer-related targets, such as Ikaros family zinc finger proteins 1/3 (IKZF1/3) and estrogen-related receptor alpha (ERRα)." (PMID 41220927, 2025). "First, we compared the fold change in expression of the ER-related receptors ESR1, ESR2, ESRRA, ESRRB, ESRRG, and GPER1 in the four female cancers." (PMID 38582811, 2024). "It has been previously documented that PLA2R1 can inhibit cancer progression by activating the Janus kinase 2 (JAK2) pathway and inducing estrogen-related receptor alpha (ESRRA)." (PMID 37345058, 2023). "The expression patterns of estrogen and its related proteins, including estrogen-related receptor alpha (ESRRA), ESRRG, ER-alpha (ESR1), and ER-beta (ESR2), were examined in the HPA in different types of cancers." (PMID 37240447, 2023). "In the present study, using Stitch EMBL, the interaction network analysis revealed that a coordination of candidate proteins (FKBP4, ESRRA, IGSF10 and ABCB5) was involved in KEGG pathways of many cancers." (PMID 36517562, 2022). "We then analyzed by RT–PCR the mRNA level of EGFR and of a small number of proteins involved in its activation and/or having prognostic value in cancer diseases: MMP-2 and -9; uPA; G Protein Coupled Receptor 1 (GPER1); Estrogen Related Receptor alpha (ERR-alpha); SRC; LDH-A and -B; HBEGF." (PMID 39329717, 2024). "ESRRA and XBP1 are known to regulate glucose, lipid, and mitochondrial metabolism while ZBTB33 is related to cell cycle progression and they have been found to be expressed in several types of cancer." (PMID 39217365, 2024). "Binding motifs for many essential TFs, such as RXRA, NFE2L2, ESRRA, IRF2, RELA, ESRRA, SOX2, and SMAD2/3, key TFs that mediate TGFβ signaling in epithelial-mesenchymal transition (EMT) and cancer metastasis, were enriched in common gained or LNC-specific gained enhancers, with some overlapping TFs." (PMID 34294701, 2021). "Using in vitro and in vivo experiments, we further show that targeting ESRRA via synthetic siRNAs could be a novel therapeutic strategy to treat OSCC and other cancers." (PMID 26639757, 2015). "Based on our in vitro and in vivo experiments, we suggest that targeting ESRRA by siRNA could be a novel therapeutic strategy for OSCC and other cancers." (PMID 26639757, 2015). "Based on our in vitro and in vivo studies, we suggest that depleting the level of ESRRA via siRNA could be a key therapeutic strategy to treat OSCC and other cancers." (PMID 26639757, 2015). "Interestingly, the ESRRA-C11orf20 fusion transcript, which is reported to be present in 15% of HG-SC patients, was absent in the 7 cancer samples sequenced." (PMID 24675677, 2014).
tumor (127 papers, 2009 to 2026). "We have previously shown that the tumor suppressor miR-125a targets ESRRA, and its downregulation causes upregulation of ESRRA in OSCC." (PMID 26639757, 2015). "Alteration in PCa cell aggressiveness was also observed in both cell lines after PPAT explant co-culture, demonstrated by a significant increase in expression levels of genes implicated in tumor cell proliferation (ESRRA) and in tumor invasive and metastatic potential (MMP-9, TWIST1)." (PMID 35978404, 2022). "For instance, inhibiting ESRRA enhances tumor cytotoxicity by promoting the recruitment of CD8+ T cells into the tumor microenvironment." (PMID 40356747, 2025). "In contrast, ESRRA expression was higher in tumor tissues than in normal tissues (p<0.0001), with a 1.1-fold increase (p<0.05)." (PMID 40900470, 2025). "Through cytokine induction and antigen-presentation stimulation, ESRRA inhibition induces tumor cytotoxicity and attracts CD8+ T lymphocytes to the tumor." (PMID 40356747, 2025). "Several nuclear hormone receptors showed changed expression in tumours with high levels of ERBB2 with some being elevated (ESRRA) whereas others were either unchanged (HNF4A) or showed reduced levels (PPARA)." (PMID 36153371, 2022). "Emerging evidence suggests that estrogen-related receptor alpha (ERRα) plays a critical role in carcinogenesis and tumor progression through various mechanisms 8-11." (PMID 35165514, 2022). "Implanted xenografts with knockdown of ESRRA expression in MDA-MB-231 cells can reduce the tumor growth rate of breast cancers." (PMID 36517562, 2022). "Their anti-tumor responses in the bone are further enhanced by the transcription factor estrogen-related receptor alpha (ERRα)." (PMID 34745140, 2021). "After transfection with siRNA to ESRRA mRNA, tumor cells demonstrated higher numbers of cells in the G2/M phase vs those in the siControl group." (PMID 32641987, 2020). "Nearly all positive cases expressed one or both of the two ESRRA-C11orf20 fusion isoforms previously observed in our tumor pool (E2-C3, E2-C4)." (PMID 21949640, 2011). "In this context, miR-137 inhibits adipogenic differentiation and may reduce lipid uptake by tumor cells by modulating the PPAR/ p160/ESRRA axis, considerably attenuating metabolic effects and suppressing prostate tumorigenesis." (PMID 40900470, 2025). "Furthermore, we confirmed significant upregulation of ESRRA, a key transcription factor involved in mitochondrial biogenesis, as has been reported previously in this tumor." (PMID 37262067, 2023). "Evidence showed ESRRA was upregulate in a large scale in tumor tissues." (PMID 34131395, 2021). "We therefore sought to explore if the knock down of ESRRA by a synthetic biostable siRNA could confer anti-tumor effect in vivo in OSCC cells." (PMID 26639757, 2015). "Previously, ESRRA has been shown to promote tumor cell proliferation." (PMID 26639757, 2015). "Based on the results of in vitro studies, we hypothesized that the depletion of ESRRA in OSCC cells might have an anti-tumor effect in vivo." (PMID 26639757, 2015). "Thus, sequence analysis provides strong evidence that the ESRRA-C11orf20 fusions in Tumor 1 are transcriptional products of a genomic rearrangement that positions ESRRA upstream of C11orf20 (rather than trans-splicing)." (PMID 21949640, 2011). "Targeted resequencing of the corresponding genomic region from two fusion-positive tumor samples identified a nearly clonal chromosomal rearrangement positioning ESRRA upstream of C11orf20 in one tumor, and evidence of local copy number variation in the ESRRA locus in the second tumor." (PMID 21949640, 2011). "It is noteworthy that, despite the lack of statistical significance for ESRRA in TGCT, CHOL, and Large B-cell Lymphoma (DLBC), a general tendency suggesting the high expression of ESRRA in advanced tumors was obvious, suggesting that ESRRA may have prognostic value in these tumor types." (PMID 40356747, 2025).
tumor (continued). "In contrast, p-eIF2α was predicted to negatively regulate tumor suppressors like the homeobox protein HOXA10, estrogen-related receptor alpha (ESRRA), polycomb group protein ASXL1, and mitofusin 2 (MFN2) function 43–46." (PMID 34330898, 2021). "ESRRA, NRF1, POLG, PPARGCA1 and SIRT1 were identified to be significantly down-regulated in all of the mtDNA-depleted tumours." (PMID 30208958, 2018). "miR-137 is a potential tumor suppressor miRNA, which negatively regulates the gene ERRα (estrogen-related receptor alpha) by targeting the two functional sites in the 3′-UTR of ERRα." (PMID 28831388, 2017). "The activated networks (HIF1A, ESRRA, ESRRG) had many proteins that were increased in tumor tissues that overlapped between the three targets, such as ENO1/ENO2, ALDOA, and LDHA." (PMID 27128972, 2016).
metabolic disorders (13 papers, 2009 to 2026). "This review will focus on the role of ESRRA in metabolism and metabolic disorders." (PMID 32121253, 2020). "One enriched network, involved in developmental disorder, hereditary disorder and metabolic disease, included genes such as EBAGT and ESRRA which are involved in estrogen binding." (PMID 33247230, 2020). "Interestingly, whole-body ESRRA knockout in mice offered some protection against DIO, so there may be differences between the whole-body vs. tissue-specific actions of ESRRA Therefore, it is not clear whether ESRRA inhibition or activation will be more beneficial for particular metabolic disorders." (PMID 32121253, 2020).
infection (8 papers, 2013 to 2025). The state of being infected such as from the introduction of a foreign agent such as serum, vaccine, antigenic substance or organism. "GM-2 and GM-3 were predominantly associated with columnar epithelial responses and included regulators such as ATF2, CDX2, FOXJ2, and AHR, with infection-induced up-regulation of TFs such as SPI1, ESRRA, RFX1, and RARA." (PMID 41042872, 2025).
bone disorder (1 paper, 2024). "Our results point to new avenues for treating bone disorders especially in clinical conditions associated with high marrow adiposity by chemically targeting ESRRA." (PMID 38704393, 2024).
ESRRA also shares sentences with these, for which no sentence is quoted: heart failure (17 papers); glioma (8); Parkinson disease (8); colon cancer (5); Hepatic steatosis (5); hepatocellular carcinoma (5); lung adenocarcinoma (5); adrenocortical cancer (4); sarcopenia (4); thyroid tumor (4); Alzheimer disease (3); autism (3); ischemia (3); prostate tumor (3); viral infection (3); acute myocardial infarction (2); adenocarcinoma (2); amyotrophic lateral sclerosis (2); autoimmune disease (2); bone tumor (2); brain injury (2); breast (2); colitis (2); COVID-19 (2); endometrioid adenocarcinoma (2); experimental autoimmune encephalomyelitis (2); injury (2); invasive ductal carcinoma (2); invasive lobular carcinoma (2); leukaemia (2).
A further 96 diseases each share a sentence with ESRRA in 2 papers or fewer.